KIAA0930 (KIAA0930)
Synonyms: C22orf9; bK268H5.C22.1; LSC3
Tractability: PROTAC: ubiquitination databases record sites on it; its protein half-life has been measured.
Gene: Protein-coding gene on chromosome 22 (45,192,244 to 45,240,944, reverse strand). Ensembl gene ENSG00000100364.
Subcellular location (Human Protein Atlas): Mitochondria; Nuclear membrane; Nucleoplasm
Gene Ontology:
Molecular function: protein binding
Genetic constraint (gnomAD): Loss-of-function variants: 24 observed, 40.33 expected, observed/expected ratio (o/e) 0.6, 90% interval 0.43 to 0.84. The upper end of that interval is the gene's LOEUF score, 0.84, which puts it in group 3 of 6, group 1 being the genes least tolerant of losing a copy. Missense variants: 456 observed, 568.28 expected, observed/expected ratio (o/e) 0.8, 90% interval 0.74 to 0.87. Synonymous variants: 257 observed, 219.85 expected, observed/expected ratio (o/e) 1.17, 90% interval 1.05 to 1.3.
Homologues: Orthologues: macaque KIAA0930 (99% identical), dog KIAA0930 (98% identical), rat Kiaa0930 (97% identical), mouse 5031439G07Rik (97% identical), guinea pig KIAA0930 (96% identical), pig KIAA0930 (96% identical), chimpanzee KIAA0930 (95% identical), tropical clawed frog KIAA0930 (87% identical), zebrafish kiaa0930 (86% identical), rabbit KIAA0930 (78% identical), Drosophila melanogaster CG9646 (45% identical), Caenorhabditis elegans C16E9.2 (38% identical).
Diseases named in the same sentence as KIAA0930 in open-access papers:
KIAA0930 is named in the same sentence as 11 diseases in open-access papers, as found by Europe PMC text mining. Sharing a sentence is not in itself a finding about the gene and the disease. The quoted sentences say what the papers report.
Cachexia (1 paper, 2023). Severe weight loss, wasting of muscle, loss of appetite, and general debility related to a chronic disease. "We believe that KIAA0930 would be a novel cachexia therapeutic target." (PMID 37477523, 2023). "Importantly, the effect was unrelated to changes in the levels of inflammatory cytokines/chemokines, indicating that KIAA0930 could be a novel target for anti-cachexia therapy." (PMID 37477523, 2023).
lung carcinoma (1 paper, 2020). "We additionally identified a suggestive association of KIAA0930-Q4X with increased risk for lung cancer." (PMID 32393777, 2020). "KIAA0930 showed significant over-expression in lung cancer compared to normal lung samples in an independent dataset from Harvard18 (P = 0.0005), while ATM showed limited variability." (PMID 32393777, 2020). "This gene is expressed in normal lung, and KIAA0930 expression is significantly upregulated in lung cancer and other carcinomas developing from epithelial cells, suggesting KIAA0930 might play a role in the development of those carcinomas." (PMID 32393777, 2020).
pancreatic cancer (1 paper, 2023). "We identified several candidates, and further study demonstrated that knockdown of the uncharacterized transcript KIAA0930 in pancreatic cancer cells alleviated muscle atrophy in vitro and in vivo." (PMID 37477523, 2023).
tongue cancer (1 paper, 2023). A malignant neoplasm affecting the tongue. "While conditioned media from pancreatic, colorectal, gastric, and tongue cancer cells caused muscle atrophy in vitro, conditioned medium from KIAA0930 knockdown cells did not." (PMID 37477523, 2023). "We found that the expression of the uncharacterized transcript KIAA0930 (C22orf9) is significantly higher in pancreatic, colorectal, gastric, and tongue cancer tissues than in normal tissues in clinical microarray datasets and that KIAA0930 knockdown reduces muscle atrophy in vitro and in vivo." (PMID 37477523, 2023).
cancer (2 papers, 2020 to 2023). A tumor composed of atypical neoplastic, often pleomorphic cells that invade other tissues. "Additionally, we observed KIAA0930 expression was significantly upregulated in the majority of carcinomas developing from epithelial cells, suggesting that KIAA0930 is a carcinoma-associated candidate gene." (PMID 32393777, 2020). "Collectively, these data strongly suggest that a reduction in KIAA0930 expression in cancer cells suppresses muscle atrophy and that KIAA0930 plays an essential role in myotube atrophy in vitro." (PMID 37477523, 2023). "Next, to investigate the function of KIAA0930 in these cancer cell lines, we established two stable KIAA0930 knockdown cell lines using lentiviral vectors encoding an shRNA targeting KIAA0930." (PMID 37477523, 2023). "Since the KIAA0930 protein is localized in the cytosol, we speculate that KIAA0930 may regulate a secretion process via the unconventional pathway and might confer a muscle atrophic phenotype in diverse cancers." (PMID 37477523, 2023). "Importantly, the effect of KIAA0930 knockdown was consistently observed in all cancer cells tested except for KD2 in CAL 27 cells." (PMID 37477523, 2023). "To show that the suppression of myotube atrophy in vitro by knockdown of KIAA0930 could be reproduced in vivo, we conducted a xenograft assay using orthotopic inoculation of cancer cells following the published method." (PMID 37477523, 2023). "KIAA0930 was not a gene included in the 468 cancer- associated genes targeted by the MSK-IMPACT study and were unable to explore germline somatic interactions for this gene in this dataset." (PMID 32393777, 2020). "Interestingly, KIAA0930 knockdown did not cause consistent changes in the secretion of inflammatory cytokines/chemokines from a variety of cancer cell lines." (PMID 37477523, 2023). "In conclusion, we demonstrate a function of the uncharacterized transcript KIAA0930 in cachexia in cancers, with a mechanism that could not be linked to the expression levels of inflammatory cytokines/chemokines." (PMID 37477523, 2023). "Although the detection limitation exists, these data suggest that factors other than Atrogin-1 and Murf-1 also could be involved in muscle atrophy and that the suppression of KIAA0930 in cancers may alleviate muscle atrophy without changes in the expression levels of cytokines/chemokines." (PMID 37477523, 2023).
KIAA0930 also shares sentences with these, for which no sentence is quoted: colorectal cancer (1 paper); endometrial cancer (1); gastric cancer (1); infection (1); oral squamous cell carcinoma (1); Tumor (1).